IGF1 (insulin like growth factor 1)
Diseases named in the same sentence as IGF1 in open-access papers (continued):
Sharing a sentence is not in itself a finding about the gene and the disease.
infection (continued). "IGF-1 levels increased significantly post-op vs. pre-op (p < 0.001) in two studies, whereas in the other study, only the obstructive group showed an increase in IGF-1 (p < 0.0001), but not the infection group (p = 0.0883)." (PMID 38276561, 2024). "If their negative impact on length gain is mediated entirely by downregulation of growth‐hormone‐induced IGF‐1 expression, infections would not be expected to reduce growth velocity before the shift to the growth‐hormone‐dependent childhood growth phase." (PMID 36111423, 2023). "Both IGF-1 and H-FABP followed the same pattern, where they showed 57.13 and 27.18% lower levels relative to control (P < 0.0001, 0.0028; respectively), then their levels progressively elevated concomitantly with infection severity." (PMID 37189123, 2023). "Estradiol implants increased circulating IGF-1 in steers grazing pastures with low endophyte infection rates but not in steers grazing pasture with high endophyte infection rates." (PMID 37143501, 2023). "However, addition of FBS with a concentration ≥10% rescued transcriptional expression of mTOR and IGF1 and 30% FBS addition significantly increased expression of mTOR and IGF1 compared to the infection group and normal group." (PMID 36423079, 2022). "In our study we found that in ISS children with confirmed H. pylori infection, both ghrelin and IGF-1 levels are significantly lower than in ISS children without this infection." (PMID 36233735, 2022). "Upon activation by infection or injury, they change into round-shaped active T cells and promote keratinocyte proliferation through the secretion of keratinocyte growth factor (KGF-1) and insulin-like growth factor-1 (IGF-1)." (PMID 32718071, 2020). "In at least two of three independent experiments, we observed significant increases in the expression of VEGF and IGF1 at 4 and 24 h post-infection, and a significant decrease in the expression of TSP1 at 24 h post-infection, comparing infected and uninfected cells." (PMID 31569536, 2019). "Coefficient estimates for IGF-1 suggest that the plasma concentration of this hormone is not an important predictor of infection intensity, as the estimated confidence interval included zero." (PMID 26380705, 2015). "Although the infection does not appear to increase IGF-1 production, the IGF-1R is activated on splenic macrophages through a yet to be identified host or parasite factor." (PMID 24967908, 2014). "Previous studies have shown that three major highly conserved signal transduction pathways, the nsy-1/sek-1/pmk-1 p38 MAP kinase pathway, the daf-2/daf-16 insulin/IGF1 pathway and the dbl-1/TGF-β signaling pathway, play significant roles in the survival of the host during infection." (PMID 24972867, 2014). "Further, we demonstrate that oHSV-D11mt infection specifically neutralized IGF2 not IGF1 within the TME, effectively abrogating the resistance conferred by IGF2/IGF1R signaling in both tumor and neutrophils/polymorphonuclear myeloid-derived suppressor cells (PMN-MDSCs)." (PMID 38853689, 2024). "However, in our study, we confirmed that if short stature in a child is accompanied by H. pylori infection, the concentrations of ghrelin and IGF-1 are lower than in short stature children and without this infection, especially among prepubertal children." (PMID 36233735, 2022). "Furthermore, the expression levels of the receptor for IGF1 (Igf1r) increased by both the protein diet restriction alone and combined with infection, although the differences were not significant." (PMID 28397794, 2017). "Although we cannot exclude the potential contribution of parasite arginase in the IGF-1 and FGF-2-mediated effects on macrophages, we found previously that L. donovani arginase contributed little to the overall arginase expression at the site of infection in this model of progressive VL." (PMID 24967908, 2014).
infection (continued). "At 10 days post-infection, L-NAME treatment in the absence of IGF1 increased infection prevalence (proportion of mosquitoes infected with at least one P. falciparum oocyst) and intensity (mean oocysts per midgut) relative to controls, consistent with previous observations." (PMID 24968248, 2014). "Genetic and biochemical experiments revealed that lin-7 modulates the DAF-2 insulin/IGF-1 signalling pathway, by binding directly to the DAF-2 RTK via LIN-2, and that both daf-16 and hsf-1 are required for the enhanced survival exhibited by lin-7 mutants upon infection." (PMID 22672310, 2012). "Since there was no clear source of infection or structural variation found in this patient that could explain her inability to wean off the ventilator, it could be proposed that her hypoxia was secondary to these changes due to IGF-1." (PMID 41589173, 2025). "To date, no investigation has been carried out on how an infection with L. intracellularis might affect the digestibility of nutrients, performance, IGF-1 status and gastrointestinal tract morphometry as a result of natural exposure when non-vaccinated and vaccinated animals are compared." (PMID 30382876, 2018). "Both wild-type HSV and rQNestin34.5v.1 significantly increased the expression of IGF2, but not IGF1, indicating that up-regulation of IGF ligands by oHSV infection is limited to IGF2 regardless of the virus type." (PMID 38853689, 2024). "Previous studies have shown that the MT biomarker LPS negatively impacts IGF-1, however, in this cohort, LPS concentrations were positively correlated with IGF-1 six and 12 months after PZQ treatment, and not at baseline during active infection." (PMID 36197916, 2022). "Levels of both regular and phosphorylated JAK1 significantly increased in ST cells upon their infection with TGEV, but not after treatment with IGF-1 or insulin." (PMID 35215353, 2022). "Addition of IGF-I to the macrophage cultures, or pre-treatment of the leishmania with IGF-1 increased L. amazonensis infection in control macrophages at 2 h of the infection, but not at 24 and 48 h (data not shown)." (PMID 31544067, 2019). "Na-butyrate supplementation alleviated the negative effects of NE infection on broiler alpha-toxin and GPD genes in the bursa tissues and increased the expression level of IGF-1 and decreased intestinal DNA fragmentation induced by NE infection." (PMID 27284219, 2016). "We found that infection with lentiviral shRNA to S6K1, but not the control shRNA to GFP, downregulated the protein level of S6K1 by ~85% (vs. control), and abolished the basal or IGF-1-stimulated phosphorylation of S6K1, in Rh30 cells, indicating the shRNA was working well in the cells." (PMID 25738366, 2015).
neurodegenerative disease (90 papers, 2009 to 2026). A disorder of the central nervous system characterized by gradual and progressive loss of neural tissue and neurologic function. "Elevated IGF-1 levels have been associated with prolonged motor neuron survival in neurodegenerative diseases." (PMID 40943847, 2025). "In humans, some studies have suggested that GH/IGF-1 treatment can contribute to brain repair and cognitive function improvement in patients suffering from traumatic brain injury, GH deficiency, and neurodegenerative diseases." (PMID 31967977, 2020). "It has also been reported that MetR is able to reduce the incidence of age-associated degenerative diseases and improve glucose metabolism by decreasing insulin, insulin-like growth factor 1 (IGF-1), and glucose levels in blood." (PMID 31739579, 2019). "Of note, IGF1 has been shown to promote the cholinergic phenotype of septal neurons and deregulation of IGF1 pathway has been implicated in neurodegenerative diseases." (PMID 29736736, 2019). "For instance, Alzheimer’s disease (AD) is a neurodegenerative disease associated with aging, and one group have shown that a reduction in IGF1 signaling rescues mice from AD-like pathology." (PMID 28203146, 2017). "On the other hand, studies looking at IGF1 in neurodegenerative diseases have been conflicting, supporting both a role for increased and decreased IGF1 signaling in the underlying pathogenesis of these diseases." (PMID 28203146, 2017). "In rodents, reduced insulin/IGF1 signaling slows aging and therefore prevents development of neurodegenerative diseases but normal aging is associated with declining levels of IGF1 and administration of insulin can improve cognitive function in AD patients." (PMID 26932723, 2016). "It has previously been shown that IGF1 signaling is linked to HD and other neurodegenerative diseases." (PMID 24929669, 2014). "What underlies the opposite effects of IGF-1 in different neurodegenerative diseases might have to do with the pathological roots of these diseases." (PMID 38094080, 2023). "Carro and Torres-Aleman suggested that IGF-1 elevation would be an early response in neurodegenerative diseases, but would gradually decrease with disease progression." (PMID 40141202, 2025). "In recent years, IGF-1 has been studied in the context of neurodegenerative diseases due to its neuroprotective and neurogenic properties." (PMID 39859255, 2025). "Higher concentrations of IGF-1 are correlated with larger brain volumes, suggesting a protective role against neurodegenerative diseases." (PMID 39335481, 2024). "Our focus in this section is the effect of IGF-1 on neurodegenerative diseases, specifically AD and PD." (PMID 36691085, 2023). "Subnormal levels of IGF-1 are found in the brain and blood in patients with neurodegenerative diseases, especially AD." (PMID 38003937, 2023). "A correlation between ER stress and IGF-1 system alterations has been proposed in several neurodegenerative diseases that share as common feature the accumulation of misfolded proteins." (PMID 35211808, 2022). "To date, however, it is still difficult to define the precise signaling of IGF-1 in neurodegenerative diseases." (PMID 35250656, 2022). "Numerous studies aimed to identify the role of estrogen, progesterone, and IGF-1 in neurodegenerative diseases." (PMID 34445359, 2021). "Although the IGF-1 level decreases with aging, the role of IGF-1 in menopause-related neurodegenerative diseases is still unclear." (PMID 34445359, 2021). "Contradictory findings with respect to the role of insulin/IGF-1 signaling in neurodegenerative disease exist." (PMID 32226608, 2020). "In animal models of neurodegenerative diseases, GH/IGF-1 administration improved cognition function." (PMID 31967977, 2020). "The prosurvival insulin-like growth factor 1 (IGF-1) signaling pathway can reduce oxidative stress-mediated neurodegenerative diseases." (PMID 31331066, 2019).
neurodegenerative disease (continued). "In the retina, controversies on the beneficial or deleterious effects IGF-1/IGF-1R levels on aging-related degenerative diseases have been reported." (PMID 30026694, 2018). "Data about the effects of GH and IGF-1 administration in neurodegenerative diseases are still insufficient." (PMID 29149058, 2017). "More complex clinical protocols are necessary to evaluate the effect of GH/IGF-1 efficacy in neurodegenerative diseases." (PMID 29149058, 2017). "With the current technology available gene therapy offers a more stable and constant “production” and “delivery” of IGF1 to treat a neurodegenerative disease like ALS." (PMID 35558521, 2016). "Along with more recent data linking brain insulin/IGF-1 function to the etiology of a number of neurodegenerative diseases will, undoubtedly, translate into more clinically oriented avenues of research in the near future." (PMID 26417600, 2015). "IGF-1 signaling is also of interest since it has many links to brain function as well as potential pathophysiological connections to neurodegenerative diseases including AD." (PMID 20863403, 2010). "Given these constraints, 4-hydroxyisoleucine’s ability to restore the IGF-1/GLP-1 signalling cascade in the brain may allow the development of a possible treatment strategic plan for this neurodegenerative disease." (PMID 35745001, 2022). "The enriched pathway analysis for 23 differentially expressed EV proteins by Ingenuity pathway analysis were enriched the Insulin Secretion Signaling pathway, IGF-1 Signaling and 14-3-3-mediated signaling, which reported to relate with neurodegenerative diseases, including AD and CTE." (PMID 34527416, 2021). "Presence of high levels of IGF-1 is therefore beneficial for the brain during youth and after an acute insult, but may be detrimental during aging and in evolving neurodegenerative diseases, which is supported by our results." (PMID 32492897, 2020). "Furthermore, it is assumed that there is a potential relationship between diminished IGF-1 levels and neurodegenerative diseases, which suggests that influencing IGF-1 levels is a promising target for efficient treatments." (PMID 30304785, 2018). "However, lack of clinical studies in human subjects about the effects of exogenous administration of GH and IGF-1, and the evolution of neurodegenerative diseases, make it difficult to draw conclusions." (PMID 29149058, 2017). "Furthermore, microRNAs differentially expressed in response to IGF1 treatment showed predicted targets which are enriched for functional annotations such as oxidative phosphorylation, neurodegenerative diseases, axon guidance, and muscle contraction." (PMID 25630602, 2015). "A protective effect of IGF-1 has been suggested in other neurodegenerative diseases." (PMID 19319184, 2009). "Thus, IGF-1 signaling involved in neuroprotection towards glutamate-induced excitotoxicity is also of critical significance for the future clinical treatment of many neurodegenerative diseases." (PMID 35203315, 2022). "In addition, our cross-disease analysis revealed that several protein complexes involved in IGF-1 regulation, contraction, synaptic vesicle cycle, collagen assembly and clathrin-mediated endocytosis were differentially targeted across neurodegenerative diseases." (PMID 34768771, 2021). "Therefore, increasing IGF-1 levels in the brain might be useful for treating a number pathologies, including neurodevelopmental disorders and neurodegenerative diseases." (PMID 28954393, 2017). "Therefore, NMDAR antagonists, especially NR2B-selective ones, combined with IGF-1 may serve as an alternative therapeutic agent for oxidative stress related neurodegenerative disease." (PMID 29029433, 2017). "Thus, the mechanism behind the increased risk of female ApoE ε4 carriers of developing cardiovascular and/or neurodegenerative diseases might involve serum levels of IGF-1 or other aspects of IIS activity reflected by these levels." (PMID 21418511, 2011).
neurodegenerative disease (continued). "In neurodegenerative diseases such as AD, critically important growth factors including brain-derived neurotrophic factor (BDNF) and insulin-like growth factor 1 (IGF-1) are downregulated, suggesting a pivotal role in the pathophysiology of AD." (PMID 32090058, 2020). "Rauskolb found the expression of IGF-1 and its corresponding receptor IGF-1R are dysregulated in patients with diabetes and neurodegenerative diseases." (PMID 30983995, 2019). "More importantly, the delivery of exogenous growth factors contained in PRP, such as EGF, IGF-1, and TGF-β, has neurotrophic effects on central nervous system (CNS) injuries and neurodegenerative diseases." (PMID 29740270, 2018). "Recently, miR-320 which is known to target IGF-1 and IGF-1R in rats is found to be up-regulated in prion-induced neurodegenerative disease." (PMID 23633914, 2012). "Concerning IGF-1, the present finding extend and reinforce the observations that level of circulating IGF-1 is altered in many type of human neurodegenerative disease." (PMID 19319184, 2009). "In addition, dysfunctions in GH/IGF-I axis are present in most neurodegenerative diseases, among which is ALS, where patients show a dysregulated expression of GH and IGF-1." (PMID 36111771, 2023). "Apart from systemic IGF-1 which is produced in the liver, IGF-1 locally produced in muscles has attracted considerable research attention in terms of the therapeutic potentials for neurodegenerative diseases such as ALS34,35." (PMID 35121777, 2022). "Considering that oxidative stress and glia-mediated inflammation also contribute to neurodegenerative diseases, the anti-inflammatory effects of IGF-1/IGF-1R still cannot be ruled out." (PMID 34445359, 2021). "Instead, together with the five upstream signalling factors (IGF1, BDNF, ZAP70, MYC, and cyclosporin A) they could help uncover the molecular mechanisms mediating AD or different neurodegenerative diseases." (PMID 26059363, 2015). "Insulin, IGF-1 and IGF-2 polypeptide and receptor genes are expressed in neurons and glial cells throughout the brain, and their highest levels of expression are in structures typically targeted by neurodegenerative diseases." (PMID 22329651, 2012). "According to others, in many neurodegenerative diseases, decreases in IGF-1 signals and lack of IGF-1 in the brain may induce apoptosis." (PMID 37296618, 2023). "The modulation of estrogen, progesterone, or IGF-1 levels alone in aging populations may not be sufficient to reverse disease progression due to the complex signal pathways in neurodegenerative diseases." (PMID 34445359, 2021). "However, the effect of oxidative stress on IGF-1 signaling and its underlying mechanism in SH-SY5Y cells, a neuronal cellular model of human source for studying human neurodegenerative disease, is not known." (PMID 29029433, 2017). "IGF-1 signals many neurodegenerative diseases and lack of IGF-1 in the brain leads to apoptosis." (PMID 22778966, 2012). "The IGF-1 system itself provides a compelling example of this principle, since localized overexpression of IGF-1Ea propeptide has been shown to protect a range of different tissues against degenerative diseases without increasing systemic IGF-1 levels." (PMID 23251442, 2012).